MIR3139 (microRNA 3139)
Synonyms: hsa-mir-3139
Gene: MicroRNA gene on chromosome 4 (143,343,460 to 143,343,535, forward strand). Ensembl gene ENSG00000265623.
Homologues: Orthologues: chimpanzee MIR3139 (100% identical).